CD44 (CD44 molecule (IN blood group))
Diseases named in the same sentence as CD44 in open-access papers (continued):
Sharing a sentence is not in itself a finding about the gene and the disease.
glioma (continued). "More importantly, silencing HAS3 or treatment with the anti-CD44 antibodies decreased the levels of the cell cycle-related proteins cyclin B1 and cyclin D1 in glioma cells, and CQ treatment further enhanced this effect." (PMID 33986244, 2021). "Future works needed to advance that this field further should focus on exploring downstream pathways through which CD44 acts its immunity role in different glioma cell types, such as tumor cells, TAMs, and T cells." (PMID 35187044, 2021). "In agreement with this, it was reported that CD44 expression was augmented in the glioma–brain interface of a G26 glioma-bearing mouse model, with single infiltrating CD44-enriched cells escaping into the brain parenchyma." (PMID 33744285, 2021). "Because immune cells are the main participants in immune response, we characterized the relationship between CD44 and the infiltrated immune cells in glioma." (PMID 35187044, 2021). "Herein, malignant glioma has relative higher CD44 expression level, and CD44 is involved in malignant progress of glioma." (PMID 35187044, 2021). "And some researchers found that the mechanism of MMP14 in glioma mainly works by cutting CD44, or via the combination of TIMP-2 and MMP14 to activate MMP-2 and MMP9 to enhance tumor invasion and tumor cell proliferation." (PMID 34712139, 2021). "CD44 transcription level is sufficient to predict OS of patients with glioma in TCGA and CGGA datasets." (PMID 35187044, 2021). "Then, to gain insight into the particular contribution of CD44 to glioma immunity, GO and KEGG analyses were used to screen relevant genes in TCGA and CGGA glioma databases." (PMID 35187044, 2021). "We next explored the effects of interfering with HA metabolism mediated by inhibiting HAS3 or CD44 on glioma progression." (PMID 33986244, 2021). "In this study, the function of CD44 was explored in glioma at bulk, spatial, and single-cell level, respectively." (PMID 35187044, 2021). "Overall, this study proposes a potential regulatory loop between CS, CD44, and integrin β1 in glioma cells, and highlights the importance of CS in CD44 stability." (PMID 34944101, 2021). "CD44 peculiarly impacts glioma outcomes in a biphasic way: high- and low-level CD44 expression both correlate with favorable survival, while intermedia CD44 level do not." (PMID 34712225, 2021). "The present study indicated that HA, hyaluronic acid synthase 3 (HAS3), and a receptor of HA named CD44 were expressed at high levels in human glioma tissues and negatively correlated with the prognosis of patients with glioma." (PMID 33986244, 2021). "We explored the expression difference of CD44 among pan-glioma transcriptome subtype, pan-glioma DNA methylation subtype, and supervised pan-glioma subtype." (PMID 35187044, 2021). "In our study, both high and low concentrations of a CD44 antibody decreased glioma cell viability, while HA only partially reversed this effect caused by a low concentration of the CD44 antibody (3 μg/ml)." (PMID 33986244, 2021). "Inhibition of HAS3 or treatment with the CD44 antibody combined with autophagy inhibitors exerted synergistic inhibitory effects on glioma proliferation through a molecular mechanism that involves arresting the cell cycle in G1 phase." (PMID 33986244, 2021). "As reported, osteopontin maintains the “stem” properties and drives radiation resistance through activating CD44 in adjacent glioma cells." (PMID 33303029, 2020). "For seven studies, glioma tissue CD44 expression was measured by immunohistochemistry, while for the rest studies, quantitative reverse transcription polymerase chain reaction (qRT-PCR) was applied." (PMID 32232385, 2020). "In the present study, by pooling the results of available cohort studies, we found that higher tumor expression of CD44 is a prognostic factor for poor survival in patients with glioma." (PMID 32232385, 2020).
glioma (continued). "The exact mechanisms underlying the potential difference between the prognostic power of higher tumor CD44 expression for survival in patients with WHO stage II–III glioma and in those with glioblastoma deserve further investigation." (PMID 32232385, 2020). "Results showed that increased CD44 expression in tumor predicted poor OS in glioma patients (hazard ratio [HR]: 1.42, 95% confidence interval [CI]: 1.02–1.97, P=0.04)." (PMID 32232385, 2020). "Taken together, these data suggest that OPN binding with CD44 in gliomas initiates a stem-promoting cascade that begins with the cleavage of CD44 ICD and results in the transcription of stem cell genes mediated by HIF-2α and CBP/p300." (PMID 33203146, 2020). "For instance, CD44 is highly expressed in gliomas; this protein interacts with HA to enhance CSC properties by activating NANOG." (PMID 33177991, 2020). "qPCR and western blot results showed that Tie1 expression in HuGSCs was significantly higher thanexpression in CD44-/CD133- glioma cells." (PMID 32174801, 2020). "CD44 and CD99 have been implicated in increasing the invasion potential of glioma cells, and were also increased in the EVs of irradiated T98G cells." (PMID 32033611, 2020). "The coordinated increase of hyaluronic acid and its receptor (CD44) in tumor tissue affects the biomechanical tension in the GBM microenvironment tightly related to invasive capacity of glioma cells." (PMID 33134175, 2020). "The role of CD44 as a surface marker of glioma CSCs has been described by several authors; interestingly, CD44 would be the most common shared marked of stemness among CSCs derived from different malignancies." (PMID 33177991, 2020). "CD44, a hyaluronic acid receptor that associates and promotes c-SRC activation and is involved in glioma cell invasion, was upregulated in almost all foci and correlated with c-SRC activation." (PMID 32680567, 2020). "Previous findings indicated that HA can significantly enhance the invasiveness of glioma cells by promoting the binding of CD44 and Moesin." (PMID 33292278, 2020). "According to our analyses of the CGGA and TCGA databases, the levels of the MSC biomarkers CD29, CD44 and CD105 were associated with the prognosis of glioma patients." (PMID 32452829, 2020). "In the GL261 murine glioma model, low expression of CD44 and CD122 was found in CD4 + and CD8 + T cells, but an increased proportion of CD44 + T cells was found in double-negative (CD4 - and CD8 -) T cells." (PMID 33381460, 2020). "Like HA, CD44 was abundant in glioma regions of TAMRA-FP hotspots but was undetectable in regions of TAMRA-FP hotspot clusters, yet these clusters were surrounded by CD44-positive cells." (PMID 32190011, 2020). "In this study, CD44+/CD133+ glioma stem cells (HuGSCs) were first isolated from surgically resected tissues from patients." (PMID 32174801, 2020). "CD44, which is expressed mostly in glioma cells of the MES subtype, can bind HA and osteopontin (OPN) allowing tumor cells to be retained in specific niches." (PMID 32570988, 2020). "We aimed to evaluate the potential predictive role of CD44 for prognosis of glioma patients in a meta-analysis." (PMID 32232385, 2020). "Previously, we have shown the increased levels of stem cell genes, including SOX2, OCT4, and GLI1 in these glioma cell lines that coincide with the presence of the CD44 and TNC in all the exosome samples from CCM." (PMID 32708613, 2020). "For example, according to the normalized RNA-seq data in the Chinese Glioma Genome Atlas (CGGA), the mRNA expression of CD44 in grade IV glioma is significantly higher than that in grade IV glioma." (PMID 33030522, 2020). "Increased expression of CD44 has been early confirmed in human glioma cells as compared with normal brain tissue, and suppression of CD44 expression decreases migration and invasion of human glioma cells." (PMID 32232385, 2020). "Glioma progression involves the interaction of phospho-moesin with CD44 and the Wnt-β-catenin pathway." (PMID 33312163, 2020).
glioma (continued). "First, we employed antibody labelling and flow cytometry to enrich CD44+/CD133+ HuGSCs from tumour tissues that were surgically resected from six patients with gliomas." (PMID 32174801, 2020). "Supporting CD44’s role in glioma aggressiveness, CD44+/+ tumors were the most aggressive, CD44−/− tumors were the least aggressive, and CD44−/+ tumors were somewhere in between." (PMID 33203146, 2020). "It has been reported that SPP1/CD44 signaling in the glioma perivascular niche promotes aggressive tumor growth, and ITGB1 was related to the dismal OS in NSCLC." (PMID 33324676, 2020). "By analyzing three glioma datasets from Gene Expression Omnibus (GEO) database, CD44 was upregulated in LGG." (PMID 33381460, 2020). "The expression level of CD44 is related to the histopathological grade of gliomas, and the monoclonal anti-CD44 antibody is capable of inhibiting the migration of glioma cells." (PMID 33381460, 2020). "In vivo, glioma cells likely employ CD44 clutches when engaging with the hyaluronic-acid-rich stroma." (PMID 32145191, 2020). "In analyzing the prognostic significance of CD44 mRNA expression in grade II–III gliomas, the two involved studies exhibit a high homogeneity." (PMID 33030522, 2020). "HA in tumors is also involved in cancer cells migration, as its production by tumor cells enables CD44 expressing glioma cells to migrate on hyaluronan-containing matrix, and the higher the density of CD44 receptors on cells' surface." (PMID 31803736, 2019). "Both CXCR4 and CD44 are highly upregulated in glioma, which further enhances the importance of studying flow in conjunction with these cancers." (PMID 31632905, 2019). "In the present study, galangin inhibited EMT and angiogenesis in glioma by downregulating CD44 expression." (PMID 31528214, 2019). "In gliomas, the cleavage of CD44 is important for tumor cell migration, invasion and adhesion and this is induced by matrix metalloproteinase-9 (MMP-9)." (PMID 29914429, 2018). "Although the functions of hyaluronan and CD44 have been previously investigated in gliomas in vitro, the roles of HASes and HYALs are unclear." (PMID 29914429, 2018). "Nonetheless, patient-derived glioma stem cells display heterogeneity in their dependence on CXCR4 versus other receptor-mediated responses to flow such as CD44 mechanotransduction." (PMID 30451884, 2018). "Human glioma cell lines produce hyaluronan and CD44, which are essential for adhesion, invasion and migration of glioma cells." (PMID 29914429, 2018). "Regarding functionalization of the substrata, it has been investigated the role of integrins and CD44 on tumour cell motility, showing how HA can increase glioma cell motility." (PMID 29300332, 2018). "Expression of CD44, which correlates with cell proliferation and phenotype stability, on the other hand, promotes the metabolic heterogeneity and plasticity of the gliomas." (PMID 30115078, 2018). "For example, HIF2-alpha was recently shown to contribute in a cooperative manner with the intracellular domain of CD44 to the acquisition of radio-resistance by glioma stem cells in a perivascular niche." (PMID 30115078, 2018). "This was confirmed by Harley and co-workers, who identified CD44 as a key driver of glioma malignancy with cells encapsulated in gelatin and PEG-based hydrogels grafted with a HA hydrogel network." (PMID 30320080, 2018). "In our study, we found that reduced LINC00461 expression reduced expression levels of some EMT markers (N-cadherin and ZEB1) and several other factors related to glioma “stemness” (CD44, SOX2, Nestin)." (PMID 29137410, 2017).
glioma (continued). "To delineate the molecular mechanisms through which APOBEC3G regulates CD44+ glioma cell proliferation and migration, we investigated intracellular signaling pathways in APOBEC3G knockdown cells." (PMID 28903341, 2017). "In conclusion, these findings indicate the importance of infiltrating MCs in glioma by modulating signaling cascades involving serglycin, CD44 and ZEB1." (PMID 28445977, 2017). "We detected the surface expression of CD28, CD45RA, CD45RO, CCR7, and CD44 in CTL and found CD28, CD45RO, and CD44 were expressed in glioma CD133+ CSC-reactive CTL, whereas CD45RA and CCR7 were rarely expressed." (PMID 28881826, 2017). "Coaxial bioprinted tumor fibers had high expression of the glioma stem/progenitor cell biomarker Nestin, mesenchymal stem cell biomarkers CD44 and Vimentin comparing to the cells mixed in alginate hydrogel." (PMID 28469183, 2017). "We postulate that increased expression of serglycin, as a main interacting partner for CD44, upon co-culture with MCs induces the CD44 expression on glioma cells to initiate a bidirectional signaling between CD44 and its surroundings." (PMID 28445977, 2017). "TGF-β signaling promotes cell proliferation and tumorigenesis in CD44-high glioma cells, therefore enhancing the capacity of cells to initiate tumors." (PMID 27527869, 2017). "One such marker that was induced in our co-cultures, CD44, is widely expressed in glioma, and showed strong and widespread cytoplasmic staining in immunohistochemistry (data not shown)." (PMID 28445977, 2017). "Flow cytometer analysis revealed that mesenchymal-like cells were positive 96 ± 1.7, 85 ± 3.5, and 95 ± 2 in low grade glioma, and 95 ± 1, 69 ± 2.5, and 82 ± 7 in high grade glioma for CD44, CD105 and CD166, respectively." (PMID 28670517, 2017). "The expression of CD133, Olig2 and CD44 was investigated using patient derived glioma stem-like cells (PDGCs) in vitro and in vivo." (PMID 28241049, 2017). "A recent study in a murine model of PDGFB-driven gliomas (resembling a proneural type GBM) showed that osteopontin secreted by tumour-associated astrocytes, via CD44 signalling promotes stem cell properties and glioma resistance to radiation." (PMID 28030801, 2017). "The putative stem cell marker CD44 was biologically validated in glioma cell lines and brain tissue samples." (PMID 28279210, 2017). "The interaction between CD44 and its ligands (e.g., hyaluronic acid and osteopontin) modulates multiple aspects of glioma biology." (PMID 28380429, 2017). "Recently, the CD90 stem cell marker has been identified as a prognostic marker for high-grade gliomas, and CD44 has been shown to be a potential metastatic marker." (PMID 27244897, 2016). "In a histopathological study, it was also established that CD44 expression was found to be correlating with the invasiveness and aggressiveness of glioma which is attributed due to its enhanced ability of migrating through the ECM55." (PMID 26370624, 2015). "The cholesterol-lowering medication simvastatin also enhances CD44 shedding; it also blocks the stimulation of glioma cell migration by oligomeric hyaluronan or EGF." (PMID 26347743, 2015). "More recently, it has been shown that a subpopulation of glioma cells characterized by high expression of CD44 and Id1 possess a stem-like phenotype." (PMID 24473088, 2014). "Recently, CD90 another stem cell marker, has been identified as a prognostic marker for high-grade gliomas and CD44 as a metastatic potential marker." (PMID 24432012, 2014). "While, CD133 seems to be expressed in proneural glioma CSCs, CD44 is highly expressed in mesenchymal glioma CSCs." (PMID 24473088, 2014). "For example, CD133+ glioma stem cells show radioresistance, and CD44+CD24− breast CSCs are chemoresistant." (PMID 23626764, 2013). "Twelve of 15 GBM samples showed strong moesin expression on the membrane of glioma cells, while eight of 15 cases showed strong membranous CD44 expression." (PMID 23855374, 2013).
glioma (continued). "Our results demonstrated overexpression of both CD44 and moesin in both glioma cell lines as compared to NHA." (PMID 23855374, 2013). "Using co-immunoprecipitation assays, we further demonstrated that moesin interacts with CD44 in glioma cells only after treatment with HA; this implicates a novel role of moesin in HA-CD44 signaling in gliomas." (PMID 23855374, 2013). "This prompted us to further investigate the role of moesin in HA-induced cell migration in gliomas in the context of CD44-HA interaction." (PMID 23855374, 2013). "Both GBM tissues and glioma cell lines (U87 / U373) demonstrated membranous expression of moesin and CD44, as revealed by immunohistochemistry and immunofluorescence, respectively." (PMID 23855374, 2013). "Our IHC results revealed an exclusive strong membranous expression of both CD44 and moesin in glioma cells in paraffin-embedded sections of GBM tissues." (PMID 23855374, 2013). "Glioma cells possess CD44 as a receptor for interacting with brain matrix hyaluronan, and secrete hyaluronidases and metalloproteinases to facilitate their migration." (PMID 23459853, 2013). "Previous data have shown that CD44 is overexpressed in neoplastic cells and aids glioma cell adhesion and invasion, through its interaction with HA and other ECM components." (PMID 22363471, 2012). "We also found that the signature is strongly correlated in gliomas with the putative stem cell marker CD44, and is highly enriched among the differentially expressed genes in glioblastomas vs. lower grade gliomas." (PMID 22493711, 2012). "Our findings indicate that CD44 and CD155 are key players in glioma progression; CD44 playing a more significant role in this context." (PMID 22363471, 2012). "CD44, overexpressed on the surface of gliomas, as well as abnormal integrins expressed by glioma cells seem to facilitate cell invasion." (PMID 24212625, 2011). "CD44 is a transmembrane glycoprotein expressed in glioma and serves as a surface receptor for components of the ECM such as hyaluronic acid (HA)." (PMID 24212955, 2011). "Interestingly, the membrane-bound metalloprotease, ADAM17, is capable of promoting the cleavage of intracellular CD44 and enhanced stemness in glioma cells via the activation of HIF-2α signaling." (PMID 40191733, 2025). "In addition to evaluating EMT, the differentiation properties of glioma cells were assessed by determining the levels of cancer stem cell (CSC) markers CD44, CD133, and Nanog." (PMID 40963691, 2025). "We found that csPCNA co-localized with the glioma stem cell markers CD44 and CD49f, providing preliminary evidence that csPCNA may be associated with a stem cell phenotype in GBM." (PMID 41463154, 2025). "The correlation analysis between ANXA5 and CD44 indicated that CD44 might play an essential role in malignant behaviors involved in ANXA5 in glioma." (PMID 40607003, 2025). "In our model, exogenous 2HG altered the expression of CD24 and CD44 in IDH-wt glioma cells." (PMID 40722659, 2025). "However, we observed a significant increase in the expression of stemness and malignancy markers such as CD133, L1CAM, Casp3, Nestin, and CD44 in surviving cells of both primary glioma and relapse cultures." (PMID 41304780, 2025). "For ANXA5, STAT1, CD44, CAV1, and ANXA2, LGG patients with high expression possessed a worse overall survival, while low expression of MAPT was associated with poor overall survival among patients with primary gliomas." (PMID 40607003, 2025). "Taken together, our data showed that ANXA5 could contribute to cell proliferation and metastasis of glioma by targeting the MAPK/CD44 axis." (PMID 40607003, 2025).